PCSK9 (proprotein convertase subtilisin/kexin type 9)
Diseases named in the same sentence as PCSK9 in open-access papers (continued):
Sharing a sentence is not in itself a finding about the gene and the disease.
colorectal cancer (22 papers, 2021 to 2025). A primary or metastatic malignant neoplasm that affects the colon or rectum. "Initially linked only to cholesterol metabolism, PCSK9 has recently been found to be overexpressed in various tumors, including colorectal carcinoma." (PMID 40563628, 2025). "As we mentioned that some studies have found that higher levels of PCSK9 are associated with increased risk of colorectal cancer and liver cancer in both men and women." (PMID 37860186, 2023). "However, it has been shown that high PCSK9 protein levels are associated with shorter survival in colorectal cancer mice with Apc and Kras mutations (Villin-Cre; KrasG12D/+; ApcMin/+), but not mice with only the Apc mutation (wildtype Kras)." (PMID 37958351, 2023). "Due to many scientific reports dealing with the negative impact of increased levels of LDLc and triglycerides on the risk of developing colorectal cancer, research has started to determine the effect of mutations within the gene for PCSK-9 on the risk of cancer development." (PMID 33808697, 2021). "Researchers found that conditioned media from colorectal cancer stem cells strongly upregulates PCSK9 expression in liver sinusoidal endothelial cells (LSECs)." (PMID 40563628, 2025). "Here we reported that methionine is catabolized to SAM and involved in DNA methylation to promote the expression of the key orchestrator of cholesterol metabolism, PCSK9, in colorectal cancer." (PMID 40125618, 2025). "Studies have demonstrated that overexpression of PCSK9 inhibited EMT in colorectal cancer cells to promote tumor metastasis." (PMID 38531630, 2024). "PCSK9 has proven to be a key player in colorectal cancer progression and metastasis by modulating tumor cell EMT and PI3K/AKT signaling, levels of macrophage migratory inhibitory factor, and lactate levels." (PMID 37103355, 2023). "In a recent biochemical study, an aptamer PL1 and Pcsk9 siRNA were able to potentiate anti PD-1/PD-L1 therapies in human colorectal cancer cells through enhancement of IFN-γ and Granzyme B expression." (PMID 36900189, 2023). "Here, the authors show that the cholesterol-uptake regulator PCSK9 drives tumourigenesis and is a therapeutic target in KRASmutant colorectal cancer." (PMID 35803966, 2022). "Immunofluorescence confirmed PCSK9 expression in LSECs of human colorectal cancer liver metastases." (PMID 40563628, 2025). "In line with this, overexpression of PCSK9 predicts shorter survival for colorectal cancer patients with APC and KRAS mutations, but not for colorectal cancer patients with only the APC mutation." (PMID 37958351, 2023). "Pre-clinical studies further elucidated that neutralizing PCSK9 during anti-PD-1 therapy could generate a synergistic anti-tumor effect for colorectal cancer, potentially by promoting CD8+T cell infiltration and inflammatory cytokine release, as well as inhibiting the recruitment of Treg cells." (PMID 40872487, 2025). "Thus, the investigators conclude that PCSK9 inhibition may be a valid adjuvant therapy for APC/KRAS mutant colorectal cancer by suppression of the KRAS/MEK/ERK oncogenic pathway." (PMID 36900189, 2023). "Moreover, previous studies revealed that the inhibition of PCSK9 might have an oncogenic role in the development and progression of colorectal cancer by inhibiting JAK2/STAT3 signaling." (PMID 37896137, 2023). "Even more, the presence of PCSK9 in LSEC is shown also at the protein level by Western blotting in cell cultures and by immunofluorescent staining in colorectal cancer liver metastasis patient tissues." (PMID 40563628, 2025). "Moreover, knockout of SREBP2 or HNF1α in colorectal cancer cells could not inhibit the expression of PCSK9 induced by methionine." (PMID 40125618, 2025).
colorectal cancer (continued). "Here it is demonstrated that methionine restriction inhibits the expression of proprotein convertase subtilisin/kexin type 9 (PCSK9), a key regulator of cholesterol homeostasis and a potential target for cancer immunotherapy, in colorectal cancer (CRC) but not in the liver." (PMID 40125618, 2025).
lung carcinoma (20 papers, 2017 to 2025). "Our analysis revealed that PCSK9 inhibitors significantly lower the risk of breast and lung cancers." (PMID 38275613, 2024). "For instance, a study demonstrated that knocking out the proprotein convertase subtilisin/kexin type 9 (PCSK9) gene can inhibit the development of lung cancer." (PMID 40722703, 2025). "A study to explore the precise role of PCSK9 in lung cancer cell apoptosis confirmed that PCSK9 siRNA had antitumor activity and induces increased apoptosis in A549 cells." (PMID 39736777, 2024). "In this drug-target MR analysis, we assessed the effects of LLDs on lung cancer risk via six LLD targets (APOB, APOC3, HMGCR, LPL, NPC1L1, and PCSK9), comprising 12 lipid-lowering pathways." (PMID 38034491, 2023). "Regarding serum PCSK9 and cancers, low circulating levels of PCSK9 antigen independently predicted a better overall survival in non–small cell lung cancer (NSCLC)." (PMID 34504788, 2021). "PCSK9, also known as neural apoptosis-regulated convertase 1 (NARC1), exhibits an anti-apoptotic function in lung cancer and neuroglioma cells." (PMID 30386595, 2018). "Conversely, PCSK9 mRNA expression was substantially lower in lung cancers (lung adenocarcinoma [LUAD] and squamous cell carcinoma [LUSC]), kidney cancers (kidney renal clear cell carcinoma [KIRC] and papillary cell carcinoma [KIRP]), and prostate adenocarcinoma (PRAD)." (PMID 38185721, 2024). "However, the role of plasma PCSK9 in predicting the efficacy of ICIs in advanced non‐small cell lung cancer (NSCLC) remains to be clarified." (PMID 34962050, 2022). "Additionally, research on PCSK9 inhibitors and malignant tumors has shown varying associations, with negative correlations observed with breast and lung cancer, but positive correlations with gastric, liver, oral, pharyngeal, and cervical cancers." (PMID 38789568, 2024). "Consistent with the significant upregulation of cholesterol in our results, the overexpression of PCSK9 in QDLS lung cancer might become a key factor in the occurrence and development of lung cancer together with cholesterol synergistically." (PMID 34838074, 2021). "For instance, PCSK9 (6.3-fold increase), CEL (15.1-fold increase), or GSTM5 (3.9-fold decrease), despite their relatively important deregulation, had only been reported in lung cancer for PCSK9, pancreatic and nasopharyngeal carcinoma for CEL, Barret esophagus and glioblastoma for GSTM5." (PMID 28962550, 2017). "In lung cancer, a pilot study has shown that serum PCSK9 levels at the second nivolumab cycle could predict overall survival (OS) in elderly patients with non-small cell lung cancer (NSCLC): low levels of circulating PCSK9 predicted better OS in elderly patients with advanced, pretreated NSCLC." (PMID 37025995, 2023).
depression (19 papers, 2020 to 2025). "PCSK9 was nominally associated with depression in an MR analysis of the LOF PCSK9 gene variant rs1159147 T allele in 479,522 UK Biobank individuals." (PMID 32595449, 2020). "A 19% increased risk of depression was also found among carriers of SNPs related to PCSK9 inhibition." (PMID 33143700, 2020). "In the univariate analysis the severity of depression (BDI-II score) was positively associated with PCSK9 circulating levels with a rise of 0.44% (β = 2.75) for every one-unit increase of BDI-II (Δ % = 0.44, 95%CI 0.23–0.65, p < 0.0001)." (PMID 33143700, 2020). "In 389 obese individuals, the Beck Depression Inventory (BDI-II) was significantly associated with PCSK9 levels." (PMID 33143700, 2020). "Interestingly, genetically predicted PCSK9 inhibition was nominally associated with increased depression risk, consistent with previous findings." (PMID 37015906, 2023). "Aim of this study was to investigate whether the presence of depression could affect PCSK9 levels in a population of obese subjects susceptible to depressive symptoms and how these changes may mediate a pre-diabetic risk." (PMID 33143700, 2020). "We performed Mendelian randomization analyses using PCSK9 levels as exposure and mood disorder traits major depressive disorder, mood instability, and neuroticism score as outcomes." (PMID 39325747, 2024). "The involvement of PCSK9 in depression was highlightened with genetic analyses studies exhibiting a positive association between increased risk of depressive mood and circulating levels of PCSK9." (PMID 36781714, 2023). "PCSK9 levels are also higher in patients with depression, correlating with depression score." (PMID 39996836, 2025). "Moreover, the effect of depression on HOMA-IR was partially mediated by PCSK9 level, providing a potential treatment strategy for the improvement of insulin sensitivity." (PMID 36387872, 2022). "In order to improve understanding of these relationships, the secondary objective was the application of the mediation analysis to ascertain if the effect of depression (independent variable) on HOMA-IR (dependent variable) was partially mediated by changes in PCSK9 levels (intervening variable)." (PMID 33143700, 2020). "Thus, considering that depression is associated with a 30% increased risk of future CV events, the reported positive association between BDI-II score and the rise in PCSK9 levels becomes of interest." (PMID 33143700, 2020). "While genetic analyses found a positive association between raised risk of depressive mood and circulating levels of PCSK9, the notion that lipid-lowering drugs might increase the risk of depression was not confirmed in trials with PCSK9 inhibitors." (PMID 33143700, 2020). "Findings from the present report, advocating the potential clinical significance of the association between depression and PCSK9 in mediating the rise in HOMA-IR, indicate that plain evaluation of the anthropometric variables may not be adequate for a full explanation of the PCSK9 changes." (PMID 33143700, 2020).
gastric cancer (18 papers, 2020 to 2025). A primary or metastatic malignant neoplasm involving the stomach. "PCSK9 was found to promote the invasion and migration of gastric cancer cells while inhibiting apoptosis." (PMID 40362754, 2025). "PCSK9 overexpression boosted gastric cancer metastasis and repressed apoptosis by supporting the MAPK signaling pathway through HSP70 upregulation." (PMID 40362754, 2025). "In syngeneic mouse models of gastric cancer, PCSK9 inhibition was demonstrated to upregulate DC infiltration and tumor cell MHC-II expression and subsequently enhance CD8+ T cell activation to realize potent tumor repression." (PMID 38600469, 2024). "Increased levels of PCSK9 in gastric cancer tissue were correlated with gastric cancer progression and poor prognosis." (PMID 38167685, 2024). "Additionally, an analysis demonstrated a significant reduction in gastric cancer (GC) risk with Proprotein convertase subtilisin/Kexin type 9 (PCSK9) inhibitors, underscoring the potential of lipid-lowering therapies in cancer prevention." (PMID 39193372, 2024). "A recent in vivo study has shown that patients with gastric cancers had higher plasma levels of PCSK9 compared to age-matched healthy controls." (PMID 36203122, 2022). "The mean s-PCSK9-Ag levels (± standard deviation; SD) were as follows: HDs, 97145 ± 20673; patients with esophageal cancer, 107136 ± 24013; and patients with gastric cancer, 101045 ± 22184." (PMID 34504788, 2021). "In addition to its roles in CRC and HCC, PCSK9 has also been shown to promote gastric cancer, BC, prostate cancer, and non‐melanoma skin cancer (NMSC), demonstrating its significant promoting role in these cancers." (PMID 40145543, 2025). "Therefore, a PCSK9i (PCSK9 inhibitor), PF-06446846, was used to treat spleen cells extracted from 615-line mice, which was a feasible mouse variety for the syngeneic gastric cancer mouse model." (PMID 38600469, 2024). "Given that PCSK9 was negatively correlated with MHC-II expression according to our bioinformatic analysis, especially in gastric cancer, we hypothesized that PCSK9 inhibition may upregulate MHC-II expression." (PMID 38600469, 2024). "Notably, previous studies have shown that PCSK9 mRNA and protein levels are significantly elevated in gastric cancer tissues and are related to tumor progression and poor survival." (PMID 38600469, 2024). "PCSK9 mediated its gastric cancer-promoting effects by upregulating HSP70 and MAPK signaling." (PMID 37103355, 2023). "Recently, PCSK9 has been reported to promote gastric cancer metastasis." (PMID 37103355, 2023). "PCSK9 silencing in gastric cancer reversed these effects and suppressed metastasis." (PMID 37103355, 2023). "For instance, PCSK9 enhances liver metastasis by maintaining high circulating cholesterol levels, whereas in gastric cancers high PCSK9 expression could promote metastasis development by activating the MAPK signaling pathway." (PMID 34359627, 2021). "As PCSK9 expression was upregulated in GC, we hypothesized that PCSK9 could play a role in gastric cancer development." (PMID 33489919, 2020). "In gastric cancer (GC), the overexpression of PCSK9 plays an important role in the development of this disease where it contributes to increased tumor aggressiveness, which is reflected by increased migration and invasion and decreased apoptosis." (PMID 36552895, 2022). "To further assess the regulatory impacts of PCSK9 inhibition on the TME, we prepared single-cell suspensions from the tumor tissues of gastric cancer-bearing mice at the experiment termination." (PMID 38600469, 2024). "In human gastric cancer, through the upregulation of heat shock protein 70 in the MAPK signaling pathway, PCSK9 promoted cell invasion and suppressed apoptosis." (PMID 38611089, 2024). "PCSK9 promoted gastric cancer invasion and migration and suppressed apoptosis but did not affect tumor proliferation." (PMID 37103355, 2023).
liver cancer (17 papers, 2021 to 2025). An epithelial or non-epithelial malignant neoplasm that arises from the liver. "Using high resolution microscopy, we were able to confirm higher mitochondrial ATP as well as excessive amount of lipid droplets accumulating in PCSK9-deficient liver cancer cells." (PMID 36612001, 2022). "Using high resolution microscopy, we were able to confirm the surge in energetic metabolic activity as illustrated by higher mitochondrial respiration and ATP production in PCSK9-deficient liver cancer cells." (PMID 36612001, 2022). "Furthermore, we performed a DMR analysis to assess the causal effects of two LDL-c lowering drugs that target HMGCR and PCSK9, respectively, on the risk of liver cancer." (PMID 37746259, 2023). "Intriguingly, PCSK9 seems to localize into the nucleus of liver cancer cells, which has never been reported before, underlining some differential and a new type of regulation and impact of this enzyme in the context of liver cancer." (PMID 36611859, 2022). "Inhibition of OX40L reverses this effect, positioning PCSK9 as a crucial modulator of TAM polarization in liver cancer." (PMID 40764998, 2025). "In recent studies on colorectal and liver cancers, more novel roles for PCSK9 in carcinogenesis have been revealed." (PMID 38185721, 2024). "On the contrary, in liver cancer, palmitoylation of proprotein convertase subtilisin/kexin type 9 (PCSK9), a key enzyme regulating cholesterol metabolism, increased affinity of PCSK9 in binding with phosphatase and tensin homolog (PTEN)." (PMID 37759431, 2023). "In this study, we investigated the causal relationship between liver cancer and SNPs related to the HMGCR and PCSK9 genes, which regulate LDL-c levels." (PMID 37746259, 2023). "Luckily enough, we are probably the first to find a connection between inactivating PCSK9 in liver cancers and the induction of ferroptosis." (PMID 36552895, 2022). "Specific targeting of PCSK9 in hepatic cancer cells showed strong beneficial outcomes and novel mechanistic insights highlighting a new player in cancer cell death by ferroptosis." (PMID 36611859, 2022). "Based on the analysis of the lipid metabolism signature of hepatic cancer cells, we targeted a specific metabolic network boosted by increased activity of PCSK9 and HMGCR enzymes." (PMID 36612001, 2022). "Lipid metabolism plays a central role in liver oncogenesis and the important role of PCSK9 in lipid homeostasis places it at the center of the stage as an attractive target in liver cancers." (PMID 36611859, 2022). "The present study aims at assessing the interest of inhibiting PCSK9 by siRNA/shRNA (short hairpin RNA) in liver cancer using different cell lines and a tumor xenograft approach." (PMID 36611859, 2022). "We provide strong evidence supporting the drug repositioning of anti-PCSK9 approaches to treat liver cancers." (PMID 36611859, 2022). "Targeting PCSK9 alone or in combination with statins deserves to be considered as a new therapeutic option in liver cancer clinical applications." (PMID 36612001, 2022). "We showed that inhibiting PCSK9 alone or in combination with HMGCR inhibition was capable of rewiring lipid metabolism of liver cancer cells, impairing their growth, migration and energetic metabolism." (PMID 36612001, 2022). "In spite of the induction of all these metabolic pathways, and the higher energy output, the treatment of liver cancer cells by anti-PCSK9 seems to be effective in reducing the viability and increasing cytotoxicity of these cells." (PMID 36612001, 2022). "In summary, the genetic inhibition of PCSK9 in liver cancer cells resulted in a decrease in cell viability and migration, an increase in the levels of intracellular lipids and led to high levels of lipid hydroperoxide." (PMID 36552895, 2022). "Statin treatment increased PCSK9 (neural apoptosis-regulated convertase-1; NARC-1) mRNA expression in human liver cancer cell line (HepG2) cells and primary hepatocytes." (PMID 33801208, 2021).